TENM4 (teneurin transmembrane protein 4)
Diseases named in the same sentence as TENM4 in open-access papers (continued):
Sharing a sentence is not in itself a finding about the gene and the disease.
ovarian carcinoma (6 papers, 2017 to 2025). A malignant neoplasm originating from the surface ovarian epithelium. "A role for TENM4 has also been proposed in the case of ovarian cancer." (PMID 33652578, 2021). "However, decreased TENM4 expression was observed in high grade serous ovarian tumors that undergo dedifferentiation, suggesting an opposite role for TENM4 in ovarian cancer." (PMID 33672732, 2021). "Indeed, a correlation between TENM4 down-regulation and shorter mean survival time was found in patients with serous carcinomas and malignant ovary tumors." (PMID 33652578, 2021). "Interestingly, TENM4 down-regulation via specific siRNA significantly decreases the sensitivity of ovarian cancer cells to cisplatin, suggesting that TENM4 may contribute to ovarian cancer drug resistance." (PMID 33652578, 2021).
neuroblastoma (5 papers, 2013 to 2021). Neuroblastoma (NB) is the most common solid, extracranial childhood tumor. "TENM4 can also be present in the tumor-derived exosomes, as demonstrated in neuroblastoma cancer cells." (PMID 33672732, 2021). "Expression of a hybrid transcript encompassing XRCC3 (X-Ray Repair Cross Complementing 3) and TENM4 sequences was detected in a further analysis of neuroblastoma." (PMID 30618566, 2018). "In support of TENM4’s possible contribution to carcinogenesis, several chromosomal rearrangements have been identified in different solid tumors, such as neuroblastoma, chronic lymphocytic leukemia, small cell lung carcinoma, esophageal carcinoma, and breast adenocarcinoma." (PMID 33652578, 2021). "The discovery of TENM4 in the human urine, in the secretome and in the exosomes of neuroblastoma cell lines might point to a potential role for teneurins as soluble blood and urine tumor biomarkers for non-invasive disease detection and management, at least for the teneurins-overexpressing tumors." (PMID 33652578, 2021). "Indeed, TENM4 peptides have been identified in a proteomic study using human urine, and TENM4 was detected as one of the most abundant proteins in the secretome and in the exosomes derived from a neuroblastoma cell line." (PMID 33652578, 2021). "Indeed, TENM4 KO neuroblastoma cells of mouse origin display decreased neurite length and ability to generate filopodia-like protrusions through FAK, Cdc42 and Rac1, whereas TENM4 overexpression in neuroblastoma cells promotes protrusion formation." (PMID 33652578, 2021). "However, structural aberrations in the TENM3, TENM4 and TENM2 genes were identified in neuroblastoma, and in the case of Ten-4, expression of gene chimeras was demonstrated by RNA-Seq, strongly supporting a functional involvement of these aberrations in tumor development." (PMID 28472127, 2017).
Tremor (4 papers, 2020 to 2025). An unintentional, oscillating to-and-fro muscle movement about a joint axis. "As far as the function of TENM4 in the central nervous tissue is concerned, studies using TENM4 Knock-Out (KO) mice have demonstrated that TENM4 plays a role in the tremor phenotype." (PMID 35011736, 2022). "The symptoms of tremor could be partly explained by abnormal TENM4 expression leading to skeletal regeneration problems." (PMID 33133146, 2020). "In addition, some ET models based on genetic studies, such as hFUS-Q290X in Drosophila and missense mutants of TENM4 in zebrafish, do not display tremor or cerebellar pathological changes." (PMID 40931016, 2025).
colorectal cancer (2 papers, 2021 to 2022). A primary or metastatic malignant neoplasm that affects the colon or rectum. "A gene expression profile of colon adenocarcinoma has demonstrated the overexpression of TENM4 during cancer progression in a mouse model that mimics human colorectal cancer development." (PMID 33652578, 2021). "Even if very few data are available for TENM4 role in cancer, decreased expression was found in serous ovarian tumors, whereas TENM4 overexpression has been revealed in colorectal cancer and TNBC, further corroborating the tumor-specific role of teneurins." (PMID 33652578, 2021). "In addition, the significant increase of TENM4 mRNA levels that were observed in tumors, compared to normal colon tissues, in a mouse model of colorectal cancer suggest that TENM4 may have a role in colorectal cancer development and progression." (PMID 35011736, 2022).
lung adenocarcinoma (2 papers, 2022 to 2024). A carcinoma that arises from the lung and is characterized by the presence of malignant glandular epithelial cells. "The ceRNA mechanism, involving genes like TENM4, XRCC2, HDAC5, CDKN1A, ARFGEF3, SNAP25-AS1, RP11-58O9.2, LINC01164, VLDLR-AS1, and RP11-14I17.2, may play a role in lung adenocarcinoma (LUAD) development linked to tumor hypoxia." (PMID 39236027, 2024).
lung carcinoma (2 papers, 2020 to 2024). "Our findings suggest a potential involvement of SNAP25-AS1, RP11-58O9.2, TENM4, XRCC2, LINC01164, VLDLR-AS1, RP11-14I17.2, and CDKN1A in the development of hypoxia-induced lung cancer." (PMID 39236027, 2024).
small cell lung carcinoma (2 papers, 2018 to 2022). Small cell lung cancer (SCLC) is a highly aggressive malignant neoplasm, accounting for 10-15% of lung cancer cases, characterized byrapid growth, and early metastasis. "Chromothripsis associated to massive rearrangements of genes between chromosomes 3 and 11, including TENM4, was also described in two small cell lung cancers (SCLCs)." (PMID 30618566, 2018).
allergic rhinitis (1 paper, 2022). Inflammation of the nasal mucous membranes caused by an IgE-mediated response to external allergens. "Exposure to diesel exhaust fumes increased the plasma concentration of TENM4, a protein involved in neural development and a risk factor for hayfever, allergic rhinitis and asthma." (PMID 35602164, 2022).
Alzheimer disease (1 paper, 2023). A progressive, neurodegenerative disease characterized by loss of function and death of nerve cells in several areas of the brain leading to loss of cognitive function such as memory and language. "Worth a mention is the downregulation of DDIT3, SMC4, and TENM4 in replicative senescence of human fibroblasts; the upregulation of SMC4 and MCM7 after vitamin C treatment; the upregulation of HOXB3 and TENM4 in Alzheimer’s disease; and the deregulation of DDIT3 and SMC4 in COVID-19 disease." (PMID 36982191, 2023).
deafness (1 paper, 2023). An inherited or acquired condition characterized by the complete loss of the ability to hear from one or both ears. "Defects in the 30 shared genes are related to several pathologies, such as vision abnormalities (TMEM135), cancer (CDH6, FZD10, TIAM2), neuropsychiatric disorders (Tenm4, Pde4dip, Grid2), deafness (TFB1M), neutrophil disorders (VPS45) and others." (PMID 36902345, 2023).
glaucoma (1 paper, 2020). Increased pressure in the eyeball due to obstruction of the outflow of aqueous humor. "Finally, hsa_circ_0023826 was identified as a biomarker for the diagnosis of glaucoma; this circRNA is encoded by TENM4 and targets miR-146a-5p, miR-3543, miR-3553, and miR-539-5p." (PMID 33133146, 2020). "By homogeneous comparisons between rats and human beings, RNO_CIRCpedia_1775 isogenous hsa_circ_0023826 was found decreased in the AH samples of glaucoma patients compared to cataract controls, while mRNA of TENM4 remained invariable." (PMID 33133146, 2020). "The hsa_circ_0023826 and mRNA of the host gene TENM4 (teneurin transmembrane protein 4) were validated in aqueous humor samples of five glaucoma patients and five cataract control patients." (PMID 33133146, 2020). "The RNO_CIRCpedia_1775 isogenous hsa_circ_0023826 in the human genome together with the source gene TENM4 was further validated in the aqueous humor of glaucoma patients." (PMID 33133146, 2020). "Together with the target microRNAs underlying the top differentially expressed circular RNAs, a new target of hsa_circ_0023826 and its host gene TENM4 were identified and further verified in the aqueous humor of glaucoma patients, indicating a promising biomarker for the disease." (PMID 33133146, 2020).
glioma (1 paper, 2021). A benign or malignant brain and spinal cord tumor that arises from glial cells (astrocytes, oligodendrocytes, ependymal cells). "The high frequency of junctions in the relatively large, yet not heavily up-regulated SHANK2 (785 kb) and TENM4 (788 kb) suggests that they are “collateral damage” of the amplifications, a hypothesis that has been described in glioma." (PMID 34891161, 2021).
heart failure (1 paper, 2021). Inability of the heart to pump blood at an adequate rate to meet tissue metabolic requirements. "For the differential genes associated LMNA alone with euchromatin, we obtained 5 candidate genes (EGR2, NMB, CREBBP, PRF1, and TENM4), of which EGR2 and NMB have been reported to involve in myocardial ischemia and heart failure, respectively." (PMID 33407844, 2021).
Hypertension (1 paper, 2017). The presence of chronic increased pressure in the systemic arterial system. "MKLN1 rs1643270 and TENM4 rs10466739 were positively associated with hypertension." (PMID 28273873, 2017).
liver disease (1 paper, 2024). "A subsequent genome-wide association study (GWAS) identified shared single-nucleotide polymorphisms (SNPs) in the genes AR, EDIL3, MACROD2, PCSK5, RUNX1T1, TENM4, and ZEB2 between PN and liver disease from the FinnGen cohort." (PMID 38397136, 2024).
liver fibrosis (1 paper, 2024). "TENM4 is also upregulated in liver fibrosis and contributes to cancer progression, although its role in the skin is unclear." (PMID 38397136, 2024).
lobular invasive carcinomas of the (1 paper, 2021). "In addition, by querying for TENM4 expression in the TCGA database through Oncomine (see “material and methods” section), TENM4 mRNA resulted to be expressed at higher levels in both ductal and lobular invasive carcinoma of the breast compared to normal breast." (PMID 33672732, 2021).
narcolepsy (1 paper, 2020). A sleep disorder characterized by a tendency for excessive sleepiness during the day which occurs even after adequate sleep in the nighttime. "Located within the gene, the functions PPP2R2C, GPM6A, EPHX2, NKAIN3, ZNF365, TENM4, and PR2Y11 are related to narcolepsy." (PMID 32358372, 2020).
prostate carcinoma (1 paper, 2017). A carcinoma that arises from epithelial cells of the prostate gland. "Other genes found to be H3K27me3-enriched in prostate cancer tissues compared to normal tissues include MYO1D, TENM4, GRIN3B, all of which are involved in cell communication and cell adhesion." (PMID 28403887, 2017).
renal carcinoma (1 paper, 2022). A carcinoma arising from the epithelium of the renal parenchyma or the renal pelvis. "The opposite correlation trend between TENM4 expression and prognosis, however, is observed in liver, endometrial, stomach, and renal cancer, in which a higher TENM4 expression correlates with reduced patient survival." (PMID 35011736, 2022).
stomach cancers (1 paper, 2021). "The possible contribution of TENM4 to cancer progression is also suggested by the correlation between TENM4 up-regulation and patients’ worst prognosis in endometrial, liver, renal and stomach cancers." (PMID 33652578, 2021).
cancer (14 papers, 2017 to 2025). A tumor composed of atypical neoplastic, often pleomorphic cells that invade other tissues. "From a therapeutic point of view, TENM4 has the features of a good tumor-associated antigen that can be used for targeting via immunological approaches, including anti-cancer vaccines." (PMID 35011736, 2022). "Of the 8 frequent mutated genes, 7 (except TENM4) were annotated in the Catalogue of Somatic Mutations in Cancer (COSMIC) and also reported in recent sequencing studies of HCC, as well as a variety of cancer types." (PMID 29333154, 2017). "Recently, rearrangements and mutations in TENM4 have been found in various cancers." (PMID 37313463, 2023). "Since cancer cell dedifferentiation is considered a hallmark of aggressiveness, these data suggest that there may be a link between TENM4 expression and patient prognosis." (PMID 33652578, 2021). "As hypomethylation is a hallmark of cancer cells and this further correlates with increased transposons activity, we investigated the methylation status of the LPP and TENM4 genes that harbor L2-derived miR-28-5p and miR-708-5p, respectively." (PMID 41441397, 2025). "Quantitative polymerase chain reaction (QPCR) analysis showed decreased expression of SNAP25-AS1, RP11-58O9.2, and TENM4 in hypoxic cancer cells compared to normoxic cells." (PMID 39236027, 2024). "Beside its well described role in organogenesis and in the development of the nervous system, TENM4 has been recently liked with cancer where its deregulated expression correlates with patients’ prognosis." (PMID 33672732, 2021). "The safety of TENM4 immune-targeting, by means of anti-cancer vaccination, could be guaranteed by the fact that its low expression is restricted to the nervous system, which is an immune privileged site." (PMID 35011736, 2022). "Few research lines have focused on the potential implication of TENM4 in cancer cell stemness." (PMID 35011736, 2022). "All these elements led us to speculate that TENM4 could regulate migration and invasion ability of cancer cells, as well as CSC properties, through activation of FAK." (PMID 33672732, 2021). "Although the data on the correlation between TENM4 expression in tumors and its release are still lacking, the possibility of using TENM4 as a disease biomarker, which can be assayed in liquid biopsies obtained from cancer patients, is an interesting field for further investigation." (PMID 33652578, 2021).
tumor (10 papers, 2017 to 2025). "While the TENM4 transcript overexpression is also associated with an increase in TENM4 protein in tumor tissue, the relative increase in LPP transcript level in tumor tissue relates to a significant decrease in LPP protein." (PMID 41441397, 2025). "A slight increase in the overall methylation throughout the TENM4 gene body can be seen in tumor vs. normal tissue in LUSC (p-value 0.013), whereas for LUAD, no statistical difference was observed." (PMID 41441397, 2025). "Data presented in this paper shows a marked increase in transcript level in tumor tissue when compared to normal tissue, suggesting an oncogenic role of TENM4 in LUAD and LUSC." (PMID 41441397, 2025). "In this work, we demonstrated the presence of significantly higher amounts of TENM4 protein in the plasma from TNBC tumor-bearing mice as compared to healthy mice." (PMID 33672732, 2021). "Since a proteomic analysis demonstrated the presence of soluble forms of TENM4 in the human urine, we checked for circulating TENM4 in the plasma of TENM4+ TNBC tumor-bearing mice." (PMID 33672732, 2021). "We then focused on plasma-derived EVs from 4T1 and MDA-MB-231 tumor-bearing mice, demonstrating higher amounts of TENM4 as compared to plasma-derived EVs from healthy mice." (PMID 33672732, 2021). "Although contradictory, taken together, these data highlight the involvement of TENM4 in tumor development and progression, and suggest its possible use as a suitable prognostic and predictive biomarker." (PMID 33652578, 2021). "A hybrid NRG1/TENM4 fusion product (γ-heregulin) displayed growth promoting activity on different tumor cell lines." (PMID 30618566, 2018). "However, the TENM4 gene transcript exhibits a pronounced increase in expression in tumor tissue compared to normal tissue, in both LUAD and LUSC." (PMID 41441397, 2025). "This might suggest an oncogenic role only for TENM4 while the LPP might function as a tumor suppressor, as suggested by other studies." (PMID 41441397, 2025). "The analysis highlighted an increase in TENM4 protein in tumor tissue compared to normal tissue, in accordance with an elevated level of TENM4 transcript, while the level of LPP protein is inversely correlated with the LPP transcript level in tumor versus normal tissue, in both LUAD and LUSC." (PMID 41441397, 2025). "In contrast, TENM4 might function as an oncoprotein, as both the transcript and protein display an increase in expression in tumor versus normal tissue, with potential implications in LUAD and LUSC pathogenesis." (PMID 41441397, 2025). "TENM4 expression is dysregulated in a variety of tumor types." (PMID 37313463, 2023). "Interestingly, besides being expressed on murine and human epithelial TNBC tumor cells, TENM4 was found to be further upregulated in murine and human TNBC-CSC." (PMID 35011736, 2022). "Moreover, we found higher levels of TENM4 in plasma from tumor-bearing mice and TNBC patients compared to the healthy controls." (PMID 33672732, 2021). "TENM4 expression has been found to be deregulated in several tumor types." (PMID 33652578, 2021). "In addition, TENM4 detection in the plasma of tumor-bearing patients endorses its potentiality as a disease detection marker." (PMID 33672732, 2021). "As in the case of LPP, the TENM4 gene also displays a varying degree of methylation depending on the region, and tumor vs. normal tissue, with no statistical significance of the methylation sites in the promoter region for normal vs. tumor tissue in both LUAD and LUSC." (PMID 41441397, 2025). "However, methylation varies between regions of the TENM4 gene body, with the first half (towards the promoter region) comprised mostly of intronic sequences, displaying the highest variations in methylation between tumor and normal tissues." (PMID 41441397, 2025). "While TENM4 gene also displays a marked increase in expression in LUAD and LUSC, in tumor versus normal tissue, this difference is less obvious for the LPP gene." (PMID 41441397, 2025).
tumor (continued). "This suggests that TENM4 is involved in CSC self-renewal, as the tumorsphere-forming assay is an in vitro surrogate of tumor-initiating potential." (PMID 33672732, 2021). "TENM4 and ACSM3, as well as CADPS and SLC35F3, were highly expressed in clusters 5 and 13, respectively, which represented two different sub-clusters in the tumor–stroma interface area." (PMID 38473208, 2024). "While a trend of increase in circulating TENM4 was observed in 4T1 tumor-bearing as compared to healthy BALB/c mice, significantly higher amounts of TENM4 were found in the plasma of MDA-MB-231 tumor-bearing mice as compared to healthy NSG mice." (PMID 33672732, 2021). "Finally, our data and in silico analyses do not support a methylation-mediated control of Ten-2 and Ten-4 gene expression in tumor cells, despite the presence of potential CpG-rich regions in both TENM2 and TENM4 genomic sequences." (PMID 28472127, 2017). "Moreover, the effects of TENM4 immunotargeting on human TNBC progression could also be elucidated by using adoptive transfer experiments in which anti-TENM4 antibodies and specific T cells, induced in immunocompetent mice, are injected into MDA-MD-231-tumor-bearing mice." (PMID 35011736, 2022). "Further in vivo experiments, which in this study are lacking, using stably TENM4 knock out murine TNBC cells that we have recently obtained by exploiting the CRISPR/Cas9 technology will help us to better define the role of TENM4 on tumor initiation and progression." (PMID 33672732, 2021).
heart disease (1 paper, 2021). "Although there are currently no reports about PRF1 and TENM4 involved in heart disease, we noticed that they may be related to LMNA mutation-associated DCM in our research; therefore, they may be the potential biomarkers of DCM, which needs further verification." (PMID 33407844, 2021).
neurodegenerative disease (1 paper, 2025). A disorder of the central nervous system characterized by gradual and progressive loss of neural tissue and neurologic function. "Tenm4 is involved in axon guidance and synaptic organization, and has been associated with myelination and oligodendrocyte function, processes that are disrupted in neurodegenerative diseases." (PMID 41282248, 2025).